EZH2 (enhancer of zeste 2 polycomb repressive complex 2 subunit)
Diseases named in the same sentence as EZH2 in open-access papers (continued):
Sharing a sentence is not in itself a finding about the gene and the disease.
chondrosarcoma (continued). "In conclusion, in this study, we describe the effect of an AdoHcy hydrolase inhibitor, DZNep, on EZH2 expression and subsequent H3K27me3 in chondrosarcomas, as well as its ability to preferentially induce death by apoptosis in tumoral cartilage cells than normal chondrocytes." (PMID 24852755, 2014). "The aim of this study was to determine whether an epigenetic therapy targeting EZH2 with DZNep may be also efficient to treat chondrosarcomas." (PMID 24852755, 2014). "However, at this point, we cannot ascertain that chondrosarcoma death induced by DZNep is directly due to EZH2 inhibition." (PMID 24852755, 2014). "Since EZH2 is highly expressed in chondrosarcomas, we hypothesized that these tumors may be a sensitive to EZH2 inhibitors, such as DZNep." (PMID 24852755, 2014). "Knockdown of EZH2 reduced the proliferative, migrated, and colony-forming capacity of chondrosarcoma cell lines and supporting the notion that EZH2 may have a role in chondrosarcoma development." (PMID 36622753, 2023). "Consistently, the data showed that SNHG6 could interact with EZH2 in chondrosarcoma cells." (PMID 33431838, 2021). "First, we investigated whether EZH2 is expressed in chondrosarcomas." (PMID 24852755, 2014). "Thus, we hypothesize that EZH2 might have a role in the chondrosarcoma." (PMID 36622753, 2023). "Compared to our results, selective EZH2 inhibitor, GSK343, and the FDA-approved EPZ-6438 (tazemetostat) were utilized to treat chondrosarcoma cell lines on colony-forming ability assay." (PMID 36622753, 2023). "In contrast to normal chondrocytes, EZH2 was highly expressed in CH2879 and JJ012 chondrosarcoma cell lines as well as increased histone 3 trimethylation at lysine 27 (H3K27me3)." (PMID 36622753, 2023). "Mechanistically, augmented SNHG6 recruited EZH2 and inhibited the transcription of tumor-suppressor gene KLF6, which thus promoted the tumorigenesis of chondrosarcoma." (PMID 33431838, 2021). "In summary, this study reveals that SP1-induced SNHG6 forms a positive loop to facilitate the carcinogenesis of chondrosarcoma through the suppression of KLF6 by recruiting EZH2, which manifests the oncogenic function of SNHG6 in chondrosarcoma." (PMID 33431838, 2021). "Interestingly, DZNep treatment induces apoptosis of chondrosarcoma cell lines whereas it has a weak effect on normal chondrocyte, and reduces cell migration, suggesting that targeting EZH2, for instance using DZNep, may be an innovative therapeutic strategy to treat chondrosarcomas." (PMID 24852755, 2014). "In contrast to cMET inhibitors, EZH2 inhibitor required higher IC50 concentrations to diminish trimethylation of histone lysine 27 (H3K27me3) and colony-forming ability in chondrosarcoma cell lines." (PMID 36622753, 2023). "In this study, we found that expression of miR-454-3p increased after HOTAIR knockdown, and we found that HOTAIR recruited EZH2 and DNMT1 to the promoter of miR-454-3p, increased DNA methylation at the miR-454-3p promoter regions and repressed miR-454-3p expression in chondrosarcoma." (PMID 28182000, 2017). "Indeed, we show that DZNep treatment significantly reduces the EZH2 protein and H3K27 trimethylation level, and induces chondrosarcoma death by apoptosis while it decreases their migration ability." (PMID 24852755, 2014). "In our chondrosarcoma model, we also found that DZNep reduces EZH2 at protein level (but not at mRNA level) and subsequently decreases H3K27me3." (PMID 24852755, 2014). "First, we showed for the first time, that human chondrosarcomas, but not enchondromas, express EZH2 protein." (PMID 24852755, 2014). "In addition, EZH2 level was more elevated in a grade II and III chondrosarcoma cell lines, SW1353 and CH2879, than in chondrocytes." (PMID 24852755, 2014). "The expression of SULF1 in chondrosarcoma cell lines treated with EPZ-6438 (tazemetostat), an EZH2 inhibitor which reduced the enzymatical activity of EZH2 without affecting its expression, was explored by western blotting." (PMID 36622753, 2023).
malignant glioma (8 papers, 2012 to 2021). A grade III or grade IV glioma arising from the central nervous system. "EZH2 has been implicated in stem cell maintenance and is overexpressed in hematological and solid malignancie`s including malignant glioma." (PMID 23077658, 2012). "They emphasized that a substantial correlation in the secretion of EZH2 and NICD1 was detected in tumor samples from GBM patients, signifying the existence of the EZH2-NOTCH1 signaling pathway in malignant gliomas." (PMID 34745848, 2021). "One of its enzymatic subunits, enhancer of zeste homolog 2 (EZH2) has been reported as oncogenic in high-grade glioma (HGG)." (PMID 30644073, 2019). "EZH2 is highly expressed in malignant glioma, and its expression positively correlates with malignancy and poor patient prognosis." (PMID 25823657, 2015). "Polycomb histone methyltransferease can silence the FOXP3 promoter through the action of its catalytic subunit EZH2, that we and others have found upregulated in GB and malignant gliomas." (PMID 23888189, 2012). "In malignant gliomas EZH2 is upregulated and maintains stemness of tumor cells by inhibiting their differentiation." (PMID 23077658, 2012). "Of note, in S24 GIC treatment with DZNep led to a downregulation of the stem cell marker nestin, which is in line with previous reports showing that EZH2 is crucial for maintaining a stem cell phenotype in malignant glioma." (PMID 23077658, 2012). "Our study also found that the EZH2 is high expression in malignant glioma cells, which might be a predictor of overall survival." (PMID 29046366, 2017). "To determine whether the antiinvasive effect of EZH2 knockdown in malignant glioma cells is mediated by AXL we used siRNA to inhibit AXL expression." (PMID 23077658, 2012). "Furthermore, EZH2 is also a known regulator of Nestin expression in malignant gliomas, which we found to be decreased in PN but not MES GICs after FTH1 knockdown in our study." (PMID 31491006, 2019).
meningioma (8 papers, 2013 to 2025). A generally slow growing tumor attached to the dura mater. "Higher levels of EZH2 overexpression were associated with shorter overall and local progression-free survival and higher proliferative activity in our grade 3 meningioma cohort." (PMID 40718644, 2025). "The inhibition of IOMM-Lee tumor cell proliferation by EPZ-6438 suggests the functional relevance of EZH2 in CNS WHO grade 3 meningioma, although the mechanisms underlying the in vitro and in vivo effects seem to be different." (PMID 40718644, 2025). "At present, the loss of H3K27me3 expression in meningioma is a poor prognostic factor, but the research of EZH2 in meningioma is rare." (PMID 36532284, 2022). "We found that EZH2 expression was associated with a worse prognosis in meningioma (P < 0.001), the same results were confirmed in the GEO database (P < 0.001)." (PMID 36532284, 2022). "The association of EZH2 expression with atypical meningiomas suggests a role for EZH2 as a marker in higher grade meningiomas." (PMID 28195122, 2017). "EZH2 expression was correlated with clinical outcome data as well as with the loss of p16 and H3 K27me3, 9p21.3 deletion, and pTERT mutational status in a cohort of 49 grade 3 meningiomas." (PMID 40718644, 2025). "Our findings demonstrate that EZH2 is functionally relevant in grade 3 meningiomas, primarily through promoting cell proliferation." (PMID 40718644, 2025). "This study primarily aims to characterize in detail the clinical and molecular correlates of EZH2 expression in grade 3 meningiomas and to investigate its functional role both in vitro and in vivo." (PMID 40718644, 2025). "Our data provide the first solid and experimental evidence for the crucial importance of EZH2 in the malignant behavior of CNS WHO grade 3 meningiomas." (PMID 40718644, 2025). "Recent multiomic studies revealed increasing expression and activity of the histone methyltransferase enhancer of zeste homolog 2 (EZH2) in parallel with the increase in meningioma grade." (PMID 40718644, 2025). "EZH2-high CNS WHO grade 3 meningiomas showed poorer OS and LPFS, although it must be acknowledged that the lack of an appropriate external validation cohort, which results from the study design, limits the generalizability of our data." (PMID 40718644, 2025). "To further explore the mRNA expression of EZH2 in meningiomas, we analyzed three datasets of meningioma cases from the GEO database and found that mRNA expression of EZH2 was higher in WHO grade 2–3 meningiomas than in WHO grade 1." (PMID 36532284, 2022). "Since several studies and GO analysis revealed that EZH2 was related to the immune response, we further explored the infiltration of immune cells in meningioma." (PMID 36532284, 2022). "We found that there was a higher EZH2 expression in WHO grade 2–3 meningiomas compared to WHO grade 1 meningioma according to the results of immunohistochemistry." (PMID 36532284, 2022). "We also further validated higher proportion of EZH2 mRNA in WHO grade 2–3 meningiomas in the GEO database, which is consistent with the immunohistochemical protein results." (PMID 36532284, 2022). "Although we have not been able to demonstrate that immunohistochemical expression of EZH2 in meningiomas correlates with immunosuppression, we found a higher tendency of PD-L1 positivity in EZH2-expressing case." (PMID 36532284, 2022). "In conclusion, our study explored the expression of EZH2 and its relationship with H3K27me3 and the immune microenvironment in meningiomas." (PMID 36532284, 2022). "In atypical meningiomas, the upregulation of enhancer of zeste homolog 2 (EZH2) that interacts with epigenetic mechanisms can be present, and it seems to be a marker of aggressiveness and higher grade." (PMID 34679551, 2021). "A recent report showed increased H3K27me3 signal and EZH2 overexpression in sporadic atypical meningiomas and a potential role of upregulated PRC2 in meningioma progression." (PMID 32724039, 2020).
meningioma (continued). "To confirm increased activity of EZH2 in atypical tumours, we next performed H3K27me3 ChIP-seq using both atypical and benign meningioma samples (n=3 each)." (PMID 28195122, 2017). "It is conceivable that DNMT1 is recruited by PRC component protein such as EZH2 to induce DNA hypermethylation in malignant meningiomas." (PMID 23349797, 2013). "The data presented here provide the first evidence that EZH2 overexpression is associated with an unfavorable outcome and higher proliferative activity as well as with 9p21.3 deletion and loss of H3 K27me3 in CNS WHO grade 3 meningiomas." (PMID 40718644, 2025). "Additionally, we explored the functional relevance of EZH2 using the human CNS WHO grade 3 meningioma cell line IOMM-Lee treated with EPZ-6438." (PMID 40718644, 2025). "Although not seen in our CNS WHO grade 3 meningioma cohort, the association of H3 K27me3 loss and poor prognosis in meningiomas of lower grades appears to contradict the inhibitory effect of EZH2 inhibition on IOMM-Lee tumor cell proliferation." (PMID 40718644, 2025). "In addition, although meningioma patients have a lower mortality rate, we still did overall survival (OS) survival analysis and the result also showed EZH2 expression predicted a worse prognosis." (PMID 36532284, 2022). "However, in analysis of immune cell differences in GEO databases, we found that the meningioma EZH2 high expression group had relatively lower CD8 T lymphocytes than the EZH2 low expression group, and it was statistically significant." (PMID 36532284, 2022). "Interestingly, we found that 12 cases with PD-L1 expression had a worse prognosis, while PD-L1 expression was concentrated in WHO grade 2–3 meningiomas, and PD-L1 expression correlated positively with EZH2-positive cases." (PMID 36532284, 2022). "The deletion of H3K27me3 in meningiomas has been considered as an important prognostic factor, but its relationship with EZH2 expression remains unknown." (PMID 36532284, 2022). "To study the correlation between EZH2, H3K27me3, and different markers of immune infiltrates in meningioma, we counted the expression of immune cells in the H3K27me3-loss samples and found that the expression of CD8 was lower in the H3K27me3-loss samples compared to H3K27me3-preserved samples." (PMID 36532284, 2022). "Interestingly, analysis of EZH2, the catalytic subunit of the PRC2 complex which acts to antagonize the SWI/SNF complex, indicated an increased expression in clear cell meningiomas compared to meningiomas with NF2 mutation (adjusted p = 1.70e-07; Suppl." (PMID 33319313, 2021). "Therefore, we aim to explore the expression of EZH2 in the meningioma and its correlation with the prognosis and immune microenvironment and lay the foundation for the subsequently potential targeted therapy and immunotherapy for meningioma." (PMID 36532284, 2022). "EZH2 may be a potential prognostic factor and therapeutic target for meningiomas." (PMID 36532284, 2022). "Therefore, it is significant to explore the expression of EZH2, its prognosis value, its relationship with H3K27me3 in meningiomas and the immune microenvironment for subsequent potential targeting and immunotherapy of meningiomas." (PMID 36532284, 2022). "However, there are limited studies on EZH2 expression in meningiomas." (PMID 36532284, 2022). "Importantly, atypical meningiomas also showed increased expression of the EZH2 gene." (PMID 28195122, 2017). "Correlations between EZH2 expression and molecular features of the CNS WHO grade 3 meningioma cohort suggest a trend for a higher incidence of clinically relevant molecular alterations in EZH2-high tumors." (PMID 40718644, 2025). "Within the CNS WHO grade 3 meningioma cohort, the OS (P < .01) and LPFS (P < .05) of patients with EZH2-high tumors were significantly shorter compared to the EZH2-low group." (PMID 40718644, 2025).
meningioma (continued). "Expression of enhancer of zeste homolog 2 (EZH2), H3 lysine 27 trimethylation (H3K27me3), and clinicopathologic parameters in meningioma." (PMID 36532284, 2022). "Correlation analysis between expression of enhancer of zeste homolog 2 (EZH2), H3 lysine 27 trimethylation (H3K27me3), and markers of immune cells in meningioma." (PMID 36532284, 2022). "We note that Samal explored the prognostic relevance of EZH2 immunohistochemistry in 149 meningioma cases, but it was limited to WHO grades 1 and 2 meningiomas." (PMID 36532284, 2022). "In this study, we aimed to investigate whether EZH2 expression levels correlate with clinical behavior and molecular features in a cohort of CNS WHO grade 3 meningiomas." (PMID 40718644, 2025). "The absence of H3K27me3 expression in meningiomas is currently considered to be a poor prognostic factor, but studies on EZH2 in meningiomas are still rare." (PMID 36532284, 2022). "These considerations suggest that cofactor-competitive inhibition of EZH2 alone may not be sufficient for the effective treatment of CNS WHO grade 3 meningiomas." (PMID 40718644, 2025). "In addition, we also analyzed the EZH2 expression positive and negative groups and we found a statistically significant difference in RFS, demonstrating that EZH2 positive expression is associated with poorer RFS in meningiomas." (PMID 36532284, 2022).
neuroendocrine tumors (8 papers, 2014 to 2024). "A recent report revealed that BTYNB can act synergistically with the EZH2-inhibitor DZNep in inducing apoptosis of neuroendocrine neoplasms." (PMID 39534570, 2024). "We aimed to analyze the expression of EZH2 in different neuroendocrine neoplasms and to correlate the expression with clinical parameters and survival." (PMID 35740494, 2022). "In this report, we identified the mRNA-binding protein IGF2BP1 as an important post-transcriptional regulator of EZH2-driven cell proliferation in neuroendocrine tumors." (PMID 35565249, 2022). "Our data identify IGF2BP1 as an important driver of tumor progression in NEN, and indicate that disruption of the IGF2BP1-Myc-EZH2 axis represents a promising approach for targeted therapy of neuroendocrine neoplasms." (PMID 35565249, 2022). "EZH2 is highly expressed in various human cancers including neuroendocrine tumors." (PMID 35565249, 2022). "Taken together, our results suggest that targeting the IGF2BP1-c-Myc-EZH2 network at various levels might be a promising therapeutic approach in neuroendocrine tumors, potentially also by using combinatorial approaches, warranting further in vivo validation." (PMID 35565249, 2022). "Consistently with these literature reports, we found that IGF2BP1 affects expression of EZH2 and its downstream effectors regulating cell proliferation, such as CDK2 and CCNE1 in neuroendocrine tumor cells, thereby driving G1/S transition." (PMID 35565249, 2022). "Thus, the selective involvement of CBX2 and EZH2 in aggressive neuroendocrine tumors may not be restricted to NEPC." (PMID 25859291, 2015).
oral cancer (8 papers, 2012 to 2024). "Recently, Milan and colleagues revealed the involvement of EZH2 in Wnt/β-catenin signaling pathway activation, which has been shown to be associated with oral cancer progression and chemoresistance." (PMID 39204206, 2024). "In particular, studies by Zhao and Cao have contributed greatly to the knowledge of EZH2’s function in oral cancer, suggesting its possible use as a biomarker as well." (PMID 39204206, 2024). "In the context of oral cancer, some studies have made a significant contribution to the understanding of EZH2’s role in OSCC." (PMID 39204206, 2024). "Thus, based on these assumptions, in this study we investigated the ability of GSK343, a selective EZH2 inhibitor, to modulate the Wnt/β-catenin signaling pathway in oral cancer using an in vitro and in vivo model." (PMID 39204206, 2024). "In conclusion, our data demonstrate that GSK343 counteracts oral cancer progression through EZH2/Wnt/β-catenin pathway modulation, suggesting that it could be a promising therapeutic approach for OSCC management." (PMID 39204206, 2024). "Enhancer of zeste homolog 2 (EZH2), an essential catalytic subunit of the polycomb 2 repressive complex (PRC2), has been reported to be associated with OSCC carcinogenesis and adverse outcomes in patients with oral cancer." (PMID 39204206, 2024). "In addition to DNA methylation, EZH2-mediated H3K27Me3 also played an important role in silencing of gene and it has been reported that EZH2 was involved in oral cancer development." (PMID 26908444, 2016). "On the other hand, mounting evidence indicate that some miRNAs could effectively repress the expression of EZH2 in tumors such as breast, prostate, endometrial, gastric, colon, hepatocellular, bladder and oral cancers." (PMID 22867052, 2012). "Zhou and colleagues showed that the EZH2 inhibitor DZNep and the siRNA against EZH2 decreased MICU1 expression and trigger cytoplasmic Ca2+ accumulation, loss of membrane potential, and changes in mitochondrial proteins involved in cell death in human oral cancer cell lines." (PMID 30011966, 2018). "Alterations in the EGFR gene copy number, or alterations in miR-7, miR-21, mRNA-KIFGA, OPN, DEPDC1B, EZH2, deltaNp63, and DNMT3B were significant for early evaluation and correlation with oral cancer." (PMID 31019584, 2019). "Notably, EZH2 emerges as a significant gene involved in regulating the STAT3/HOTAIR axis, influencing HNSCC proliferation, differentiation, and promoting metastasis by modulating related oncogenes in oral cancer." (PMID 38600608, 2024).